ALB (albumin)
Diseases named in the same sentence as ALB in open-access papers (continued):
Sharing a sentence is not in itself a finding about the gene and the disease.
End Stage Liver Disease (134 papers, 2008 to 2026). Final stage of a liver disease when the liver failure is irreversible and LIVER TRANSPLANTATION is needed. "Patel’s study reported similar risk factors, such as higher INR and lower serum albumin levels for patients with end-stage liver diseases." (PMID 40817221, 2025). "Traditional scoring systems, including Child–Pugh, Albumin–Bilirubin, Model for End-Stage Liver Disease (MELD), MELD-Na, MELD 3.0, and Alpha-fetoprotein scores, are widely used but often fail to provide precise risk assessments." (PMID 41536859, 2026). "Commonly used liver assessment tools like the Child-Pugh score, Model for End-stage Liver Disease, and Albumin-Bilirubin score were primarily developed for chronic liver disease or non-infectious liver failure." (PMID 41378216, 2025). "High alpha-fetoprotein (AFP), high C-reactive protein (CRP), low albumin, and an increase in Model for End-stage Liver Disease (MELD) and Child-Turcotte-Pugh (CTP) scores were found to have a negative impact at three months." (PMID 40385925, 2025). "Serum albumin levels are reduced in various conditions, such as inflammation, protein malnutrition, end-stage liver disease, or malignancy." (PMID 39026682, 2024). "Mean albumin-bilirubin (ALBI)-score as well as (modified)-model for end-stage liver disease (MELD)-scores were higher in patients with congestive hepatopathy." (PMID 37378679, 2024). "Patients with end-stage liver disease typically experience a decrease in albumin levels, which appears to be highly effective in the prediction of prognosis in cirrhotic patients." (PMID 38201348, 2023). "Some studies have revealed that smoking, the Child–Pugh score (CTP), the Model for End-Stage Liver Disease (MELD) score, the serum albumin (ALB) level, and the ammonia level are associated with the presence of MHE." (PMID 34055016, 2021). "In patients with end-stage liver disease, different metabolites and drugs that cannot be detoxified are bound to albumin." (PMID 34492024, 2021). "Its accuracy was significantly better than that of Child–Pugh, model of end-stage liver disease, albumin-bilirubin score, D’Amico model, Augustin model, AIMS65 score and Glasgow-Blatchford score." (PMID 33198637, 2020). "Among cirrhotic patients, lower Model for End-Stage Liver Disease (p = 0.0258), higher albumin (p = 0.0015), and higher glomerular filtration rate (p = 0.0366) were related to SVR." (PMID 29990371, 2018). "Using a database of all potential liver transplant recipients in the United States, we describe the association between serum albumin, MELD and mortality among patients with end-stage liver disease." (PMID 23349678, 2013). "Combined LF scores, such as the Child–Pugh score, the model for end-stage liver disease score, and the albumin–bilirubin score, demonstrated usefulness in assessing the risk of RILD within 3–4 months after radiotherapy in either conventional or ablative radiotherapy." (PMID 38326881, 2024). "However, there is some evidence supporting the use of albumin particularly in patients with end-stage liver disease." (PMID 37218881, 2023). "Although he received spironolactone, furosemide diuresis, albumin infusion, and intravenous antibiotics, the model for end-stage liver disease (MELD) score continued to increase to 29 points on 9 November 2018, and he was finally placed on the waiting list for liver transplantation." (PMID 36992343, 2023). "The second hypothesis for the superiority of MELD 3.0 over MELD-Na-KT is that albumin plays a significant role in determining the prognosis of end-stage liver disease patients." (PMID 38201348, 2023). "In the previous report, a stepwise increment in depressive state score by frailty score was shown, and compared with non-frail patients, the frailty patients had higher model for end stage liver disease scores, lower serum sodium and albumin levels and higher prevalence of hepatic encephalopathy." (PMID 32605049, 2020).
End Stage Liver Disease (continued). "Alcohol consumption, use of antituberculosis drugs, serum total bilirubin, direct bilirubin, total protein, albumin, thrombinogen time, international normalized ratio, and the model for end-stage liver disease (MELD) score were significantly correlated with DILI-associated mortality." (PMID 26702391, 2015). "A potential disadvantage of including serum albumin in liver allocation decisions is that intravenous albumin administration - a common practice in patients with end-stage liver disease - may lower a patient's likelihood of transplantation." (PMID 23349678, 2013). "This is mainly because hepatic synthesis of albumin tends to decrease in end-stage liver disease." (PMID 21179323, 2010). "Under substitution of albumin and fluids to maintain central blood volume, there was a simultaneous improvement of renal function that may be relevant in patients with end-stage liver disease." (PMID 18197961, 2008). "Optimal administration of albumin may improve patient outcomes and reduce the burden of these conditions on the healthcare system, especially in patients with advanced complications of end stage liver disease." (PMID 38899040, 2024). "Based on these data, albumin has been proposed to be an immune restorative drug, and albumin supplementation touted as a potential therapeutic strategy by which to restore immune competency and prevent nosocomial infections in patients with end stage liver disease." (PMID 39502706, 2024). "However, impaired synthetic functions accompanying end-stage liver disease needs to be considered as an additional determinant of reduced serum albumin that may have contributed to the results reported." (PMID 22433965, 2012). "The most widely used systems are the Model for End-Stage Liver Disease (MELD) and Albumin–Bilirubin Ratio (ALBI)." (PMID 41156273, 2025). "Significant differences were found in aspartate aminotransferase and albumin values, prothrombin time, platelet count, FIB-4 index, Child–Pugh grade, model for end-stage liver disease score, endoscopic variceal form, and RC sign between the groups (P < 0.01)." (PMID 39470783, 2025). "Existing tools [Child-Pugh, model for end-stage liver disease (MELD), MELD-sodium (MELD-Na), Albumin-Bilirubin (ALBI), and platelet ALBI (PALBI)] have limitations, including subjectivity, complexity, and reliance on logarithmic transformations." (PMID 41549846, 2025). "Common predictors of response reported for both arms were Child-Turcotte-Pugh score, model for end-stage liver disease (MELD) score, serum urea, serum albumin, and prothrombin time on multivariate analysis for multiple trials." (PMID 38285703, 2024). "PALBI: Platelet-Albumin-Bilirubin Score, CTP: Child-Turcotte-Pugh Score, MELD-Na: Model of End-Stage Liver Disease-Sodium Score, AUC: Area under the curve, PPV: Positive predictive value, NPV: Negative predictive value." (PMID 39027759, 2024). "Various parameters, including pre- and post-treatment model of end-stage liver disease (MELD) score, serum albumin (ALB), total bilirubin (TB), coagulation function, aminotransferase, and survival rate, were evaluated." (PMID 37742014, 2023). "In patients with end-stage liver disease (ESLD), albumin is often used as both medication and/or as volume replacement." (PMID 37218881, 2023). "Model of end stage liver disease (MELD) and albumin‐bilirubin (ALBI) scores were comparable between the groups." (PMID 37649859, 2023). "The radiomics model and the clinical–radiomics model were compared with the clinical model comprising clinical variables and other clinical predictive indices, including the model for end-stage liver disease (MELD) score and albumin–bilirubin (ALBI) score." (PMID 37958476, 2023). "In clinical practice, liver reserve function is often evaluated by Child-Pugh (CP) score, indocyanine green 15-min retention rate (ICG-R15), albumin-bilirubin (ALBI) score, and model for end-stage liver disease (MELD) score." (PMID 36561314, 2022).
End Stage Liver Disease (continued). "Pitted erythrocytes correlated with albumin (p = 0.024), bilirubin (p<0.001), international normalized ratio (INR; p = 0.004), model of end-stage liver disease (MELD) score (p<0.001) and liver stiffness (p = 0.011)." (PMID 35849612, 2022). "The outcome measures were survival rate, model of end-stage liver disease (MELD) score, albumin, total bilirubin, coagulation function, and aminotransferase." (PMID 35578365, 2022). "The albumin bilirubin (ALBI) score and model of end stage liver disease (MELD) are based on routine daily investigations." (PMID 34319020, 2021). "We also compared the nomogram with APASL ACLF research consortium (AARC) score, model for end-stage liver disease (MELD) score, MELD with serum sodium (MELD-Na) score and albumin-bilirubin (ALBI) score." (PMID 34911462, 2021). "These quantitative systems are based on laboratory parameters such as the albumin-bilirubin (ALBI) grade, the Model of End Stage Liver Disease (MELD) score, and the MELD-Natrium score." (PMID 34638502, 2021). "Various clinical scores have been established as predictors of mortality in DeCi patients, such as the Child-Turcotte-Pugh (CTP) score, the Model for End-stage Liver Disease (MELD) score and albumin-bilirubin (ALBI) score." (PMID 34336902, 2021). "Positive associations were found between sCD163 levels and the Child-Turcotte-Pugh (CTP), Model for End-Stage Liver Disease (MELD) and albumin-bilirubin (ALBI) scores." (PMID 34336902, 2021). "The alpha fetoprotein (AFP), albumin, and GGT levels were higher in the HCC group; however, total bilirubin, INR, model for end-stage liver disease (MELD) scores, and Child–Pugh scores were higher in the non-HCC group (P < .001)." (PMID 32176089, 2020). "Data are provided as the median (IQR); MELD: model for end-stage liver disease; i-MELD: integrated-MELD; MDF: Maddrey's discriminant function; NLR: neutrophil-to-lymphocyte ratio; NLA:100 × (neutrophil − to − lymphocyte ratio)/albumin." (PMID 33415154, 2020). "The albumin-bilirubin (ALBI) score, the model of end-stage liver disease (MELD), and the Child-Turcotte-Pugh (CTP) score were calculated as standards of reference for hepatic function." (PMID 31001679, 2019). "Grading systems, such as the albumin-bilirubin ratio (ALBI) score, the Child-Turcotte-Pugh (CTP), or the model of end-stage liver disease (MELD), combine these parameters to determine liver function and are used for treatment decision-making." (PMID 31001679, 2019). "The model of end-stage liver disease (MELD) score, The international normalized ratio(INR), serum albumin and bilirubin levels were assessed at 0 (baseline), 3 and 6 months after cell transplantation." (PMID 31210432, 2019). "The outcome measures were total bilirubin (TBIL), alanine transaminase (ALT), international normalized ratio (INR), albumin (ALB), and the model for end-stage liver disease (MELD) score." (PMID 29747694, 2018). "We applied RAM, albumin-bilirubin (ALBI), and model for end-stage liver disease (MELD) scoring systems to predict early mortality and early recurrence in HCC patients after surgery." (PMID 29121890, 2017). "The AKI group had significantly higher model for end-stage liver disease and sodium (MELD-Na) score, lower albumin level, and longer hospital stay after surgery than the non-AKI group." (PMID 25342079, 2014). "As such, albumin was excluded from the final MELD model; however, it is a component of the Pediatric End-Stage Liver Disease (PELD) score used to prioritize pediatric liver transplant candidates." (PMID 23349678, 2013). "However, the Rad-score alone did not demonstrate a better performance than the Child–Pugh (CP) score, model for end-stage liver disease (MELD), and albumin–bilirubin (ALBI)." (PMID 40806948, 2025).
End Stage Liver Disease (continued). "Previous studies have reported other noninvasive methods, such as the albumin-bilirubin (ALBI) grade, platelet-albumin-bilirubin (PALBI) grade, Child-Pugh (CP) grade, and Model for End-Stage Liver Disease (MELD) score to predict the occurrence of rebleeding events, with a high C-index." (PMID 35692881, 2022). "Parenclitic deviations along albumin-bilirubin (Hazard ratio = 1.063, p < 0.05) and albumin-prothrombin time (Hazard ratio = 1.138, p < 0.05) predicted 12-month survival independent of model for end-stage liver disease (MELD)." (PMID 36926100, 2022). "The accuracy of the nomogram was evaluated and compared with traditional models, like CP score (Child-Pugh), MELD score (Model of End-Stage Liver Disease), and ALBI score (albumin-bilirubin) by using receiver operating characteristic (ROC) curve, calibration curve, and decision curve analysis (DCA)." (PMID 34277414, 2021). "A meta-analysis was performed to assess the effect of BM-MSCs on liver function indicators, including Models of End-Stage Liver Disease (MELD) score, serum albumin (g/L), total bilirubin (mg/dl), Prothrombin concentration (%), and alanine aminotransferase (ALT) (U/L)." (PMID 25861263, 2015). "The following pretreatment factors were not significantly related with a decline in posttreatment liver function: ALP, albumin, HGB, CP class, model for end-stage liver disease (MELD) score, BCLC stage, portal vein thrombus at baseline, radioactivity, dose, and bilobar treatment." (PMID 26779437, 2015).
Encephalopathy (131 papers, 2006 to 2026). Encephalopathy is a term that means brain disease, damage, or malfunction. "APACHE II, SOFA, age, tau protein, IL-6, and albumin were associated with sepsis-related encephalopathy and were supported by medium- to high-quality evidence." (PMID 38835794, 2024). "The higher total bilirubin-albumin ratio increased the risk of bilirubin encephalopathy by 23% (OR = 1.23, 95% CI: 1.16–2.48)." (PMID 31950971, 2020). "We identified three important factors that were independently associated with survival: serum bilirubin, serum albumin and encephalopathy." (PMID 30367628, 2018). "Albumin dialysis was associated with significant improvement in encephalopathy (p = 0.02), and a decrease in total amino acid levels (2490 ± 152 μM to 2229 ± 114 μM, p < 0.001)." (PMID 19175915, 2009). "The final model has four variables: age, encephalopathy, serum bilirubin, and serum albumin to obtain a risk score (R) for each patient using the formula R = (0.0484 × [Age in Years] + 0.469 × [encephalopathy] + 0.537 × Loge [Bilirubin in μmol/L] - 0.052 × [Albumin in g/L]." (PMID 26203357, 2015). "On the other hand, other studies showed significant improvements in serum albumin levels and encephalopathy following the BRTO procedure." (PMID 40486449, 2025). "Hypoproteinemia can elevate the free concentration of drugs in the bloodstream, and our patient had a serum albumin concentration below 30 g/L before the onset of encephalopathy." (PMID 40550058, 2025). "Monitoring in an intensive care unit is necessary for patients with lower albumin, along with careful assessment of their neurological condition and encephalopathy severity." (PMID 40529137, 2025). "In a phase I trial, patients receiving 260 mg/m2 of albumin-bound paclitaxel experienced grade 2 and 3 encephalopathy with low-intensity pulsed ultrasound and concomitant administration of intravenous microbubbles (LIPU-MB)." (PMID 39207625, 2024). "We found that above a cut-off of ≥7.5 for the TAI (total bilirubin, albumin, and international normalized ratio (INR)) score used in our study, the risk of developing encephalopathy increased 14.4-fold." (PMID 38496192, 2024). "The MARS is a commercially available system used to filter out albumin-bound toxic metabolites, which eventually lead to encephalopathy and multi-organ failure." (PMID 35882727, 2022). "Compared with the control group, those with bilirubin encephalopathy have higher bilirubin-albumin ratio (13.8 ± 3.6 vs. 10.6 ± 2.5, P=0.000)." (PMID 31950971, 2020). "Elevated subscores (≥ 2) for the laboratory and clinical parameters were reported in 53% for prothrombin time, in 56 % for bilirubin, in 53 % for albumin, in 52% for ascites, and in 42% for encephalopathy." (PMID 32249336, 2020). "In the present study, we found that there was a positive correlation between bilirubin-albumin ratio level and bilirubin encephalopathy." (PMID 31950971, 2020). "Likely contributing factors to the ifosfamide-induced encephalopathy seen in this patient were her advanced age, low albumin, renal impairment manifesting in deranged electrolytes and the addition of aprepitant to her regimen." (PMID 33292592, 2020). "On the other hand, in studies with multivariate analysis, Child-Pugh and MELD scores and their components, such as albumin, bilirubin, prothrombin time, encephalopathy, and age, were the variables most related to prognosis." (PMID 30941330, 2019). "This scoring system is composed of ascites, bilirubin, albumin, prothrombin time, and encephalopathy that were considered to be crucial in evaluating liver reserving functions of patients with chronic liver diseases as well as HCC." (PMID 28673346, 2017). "FLV ratio was highly correlated to both CTP and ALBI composite scoring systems, but only somewhat correlated to albumin, bilirubin, and encephalopathy." (PMID 27349530, 2016).